FOXA1 (forkhead box A1)
Diseases named in the same sentence as FOXA1 in open-access papers (continued):
Sharing a sentence is not in itself a finding about the gene and the disease.
breast carcinoma (continued). "In breast cancer, however, high levels of FOXA1 are a marker of good prognosis possibly because elevated FOXA1 in breast cancer engenders a greater reliance upon ligand-dependent ER activity to drive tumorigenesis, which in turn would generate hypersensitivity to anti-oestrogen therapies." (PMID 23420418, 2013). "The genomic region encompassing the FOXA1 gene (14q21.1) is amplified in a range of cancers and there is increasing evidence this also occurs in prostate and breast cancer." (PMID 23420418, 2013). "Therefore, data published to date suggest that FOXA1 is a major determinant of estrogen–ER activity in breast cancer." (PMID 23192763, 2013). "In breast cancer, FOXA1 has been shown in multiple studies to be an independent marker for good outcome; most probably because the presence of FOXA1 indicates a functional ER complex which will respond well to anti-oestrogen compounds such as Tamoxifen." (PMID 23420418, 2013). "Binding of Foxa1 to its targets was shown to be required for chromatin-association of androgen receptor (AR) in prostate cancer cells, and the estrogen receptor (ER) and retinoic acid receptor (RAR), in breast cancer cell lines." (PMID 22737085, 2012). "Hurtado and colleagues have reported that FOXA1 is necessary for estrogen to regulate expression of numerous genes in breast cancer cells, and we have just shown that Foxa1 and Foxa2 cooperate in mediating the effects of estrogens and androgens on liver cancer risk in response to carcinogens." (PMID 22737085, 2012). "Finally, we reveal that PBX1 and FoxA1 can co-occupy specific genomic regions in breast cancer cells." (PMID 22125492, 2011). "This could serve as model to study ER-α/FOXA1-mediated gene regulation, and to refine further the molecular classification of ER(+)-type breast cancers." (PMID 20565980, 2010). "Recent studies also suggest FOXA1 as a favourable prognostic factor in breast cancer, with potential relevance in the subclassification of luminal/ER-positive tumours into two subgroups with different biological behaviour and prognosis, the luminal A and the luminal B." (PMID 19549328, 2009). "Interestingly, only FOXA1-positive expression showed a clear protective effect for breast cancer relapse in this cohort of patients with poor prognosis." (PMID 19549328, 2009). "Microarray analyses have revealed that forkhead box A1 (FOXA1) and GATA binding protein 3 (GATA-3) are expressed in close association with ERα, both encoding for transcription factors with a potential involvement in the ERα-mediated action in breast cancer." (PMID 19549328, 2009). "FOXA1 negativity is strongly related to breast cancer recurrence, this association being very close to statistical significance (FOXA1-negative vs. FOXA1-positive: hazard ratio = 7.02, 95% confidence interval = 0.92 to 53.37; P = 0.060)." (PMID 19549328, 2009). "Moreover, in order to quantify the risk of these survival associations, univariate analysis was performed for FOXA1 and GATA-3 as well as for the classical prognostic factors in breast cancer." (PMID 19549328, 2009). "In addition, FoxA1 is known to cooperatively interact with estrogen receptor in breast cancer cells." (PMID 18798982, 2008). "A separate study suggested that Twist1 downregulates the expression of FOXA1 to increase the level of choline kinase in estrogen receptor-negative breast cancer cell lines, thus providing environmental advantages for cancer cells and promoting the metastasis of breast cancer." (PMID 40003882, 2025). "Meanwhile, FOXA1, closely linked to tumor chemoresistance, enhances EMT, metastasis, and chemoresistance in docetaxel-resistant LAD cells, and its upregulation in endocrine therapy-resistant breast cancer promotes drug resistance via transcriptional regulation of downstream genes." (PMID 40623983, 2025).
breast carcinoma (continued). "Understanding the mechanisms regulating NIS, its influence on cellular processes such as migration and metastasis, and its connection with transcription factors like FOXA1 could contribute to the development of new therapeutic strategies for breast cancer treatment." (PMID 41283251, 2025). "Thus, FOXA1 may serve as a key determinant of ER transcriptional programs and endocrine responses in breast cancer." (PMID 38605023, 2024). "Therefore, the diabetes-related medicine metformin and FOXA1 gene inhibition might be a new treatment for patients with HR+ breast cancer when combined with tamoxifen, an endocrine therapy." (PMID 39000600, 2024). "Interestingly, a proteolysis-targeting chimera (PROTAC) degrader of the SWI/SNF ATPase subunits has been investigated in prostate cancer models and ERα positive ZR-75-1 breast cancer cells, which showed FOXA1-driven cancer cells to be significantly sensitive to SWI/SNF attenuation." (PMID 39282472, 2024). "Therefore, interfering with FOXA1 transcriptional reprogramming in TAM-R breast cancer may be an effective strategy to overcome drug resistance in breast cancer." (PMID 38605023, 2024). "The cell proliferation in hormone-receptor-positive breast cancer (HR+ BC) cell lines MCF-7 and T47D was significantly decreased with the loss of FOXA1." (PMID 39000600, 2024). "Overall, these results demonstrate that metformin and FOXA1 deletion assists the tamoxifen-mediated cancer spheroid formation inhibition in hormone-receptor-positive breast cancer (HR+ BC) cells." (PMID 39000600, 2024). "We found that the deletion of the FOXA1 gene decreased the cancer cell spheroid formation in the hormone-receptor-positive breast cancer (HR+ BC) cell lines using 3D ex vivo." (PMID 39000600, 2024). "Therefore, it remains to be explored whether there is a statistical interaction between AGR2 and FOXA1 on the prognosis of breast cancer." (PMID 37568077, 2023). "Interestingly, the expression of AGR2 in breast cancer cells required the transcription factor FOXA1, and our findings suggested that only decreasing the expression of FOXA1 could not entirely prevent the corresponding signal pathway." (PMID 37568077, 2023). "Furthermore, the results from our WGCNA analysis indicated the existence of unknown networks between INO80 and a subset of luminal breast cancer biomarkers, including FOXA1, ESR1, GATA3, TFF1, and AR." (PMID 38020889, 2023). "In agreement with a pattern recently reported in primary breast cancer, several genes from the highly intercorrelating gene cluster associated to hormone responsiveness (AR, PGR, ER signaling, ESR1, and FOXA1) emerged as interesting prognostic markers for MBC, both when expressed in PT and in DM." (PMID 38449790, 2023). "Furthermore, cDNA microarray cluster result analysis associates FOXA1 gene transcripts with other genes, such as ER, GATA-3, and X-box binding protein [XBP-1], and this is a characteristic feature of the luminal subtype A of breast cancer." (PMID 37626655, 2023). "Thus, we hypothesize that FOXA1-driven AR expression in TNBC-basal SNAI1-mutant cells triggers a transcriptional program reminiscent of ER-mediated transcription in luminal breast cancer, whose exact mechanism awaits further investigation." (PMID 36171192, 2022). "Thus, the inhibition of FOXA1 and ERα expression could represent another major mechanism for the PR-mediated anti-estrogenic effect in breast cancer cells." (PMID 36009407, 2022). "Therefore, it is clear that FOXA1 is a therapeutic target for HR + breast cancer." (PMID 36292640, 2022). "Finally, we experimentally (i) confirmed the effect of FOXA1 expression on DNA methylation patterns at regions bound by FOXA1 in the MCF-7 breast cancer cell line, and (ii) detected interactions of FOXA1 with TET1 and TET2 proteins both in an in vitro setup and at endogenous levels." (PMID 35440061, 2022). "The notion of transcription factor addiction may be true for FOXA1 in HER2+/ER− breast cancer." (PMID 33980863, 2021).
breast carcinoma (continued). "Hence, FOXA1 is a pioneering factor for ER-stimulated gene expression in breast cancer cells." (PMID 34680352, 2021). "Indeed, factors affecting the balance of ER and FOXA1 binding to estrogen response elements, such as forced overexpression of FOXA1, may promote expression of genes involved in metastasis and endocrine-resistant breast cancers." (PMID 34922480, 2021). "However, differences in ER and FOXA1 cistromes within male breast cancers were capable of segregating patient outcomes, suggesting that FOXA1 may influence epigenetic regulation of chromatin in a gender-specific manner." (PMID 34680352, 2021). "Thus, ongoing efforts to disrupt FOXA1 as a means to augment treatment of ER+ breast cancer may be useful for HER2+/ER− disease as well." (PMID 33980863, 2021). "Thus, FOXA1 regulates anchorage-independent growth in breast cancer cells." (PMID 33417085, 2021). "Since GATA3 has been reported to interact with menin in lymphocytes, and menin is known to interact with one member of the FOXA family, FOXA2, we performed immunoprecipitation (IP) and PLA analyses to determine whether menin could interact with GATA3 and FOXA1 in breast cancer cells." (PMID 34561764, 2021). "Notably, one of them is FOXA1 (forkhead box A1), also known as HNF3α (hepatocyte nuclear factor 3α), a transcription factor that impacts estrogen receptor signaling and is key to mammary ductal development and progression of luminal A subtype breast cancer." (PMID 34425866, 2021). "Notably, FOXA1 is also independently prognostic of improved outcomes of patients with ER-positive disease as well as response to endocrine therapy, supporting an essential function of FOXA1 in luminal breast cancer." (PMID 34680352, 2021). "Thus, APTR/miR132-3P/FOXA1 axis possibly contributes in the pathogenesis of breast cancer." (PMID 34094972, 2021). "In addition to the desired systemic effects of glucocorticoids, it is important to recall that GR is expressed in 50–70% of breast cancers, is highly correlated with ER and FOXA1 expression, and is prognostic of favorable patient outcomes when examining all breast cancers as a group." (PMID 34680352, 2021). "Thus, their interaction with cancer related axes including FOXM1/GATA3/FOXA1/ESR1 axis might affect the course of breast cancer." (PMID 34094972, 2021). "To further verify the regulation roles of FOXA1 on DSCAM-AS1, we knocked down FOXA1 by siRNAs in lung adenocarcinoma, breast cancer, and prostate cancer cell lines, respectively, qPCR and Western blotting showed these siRNAs could effectively silence FOXA1 levels." (PMID 32929382, 2020). "Furthermore, developing molecular targeted therapies against dysregulated FOXA1 expression in EMPD is tempting, as the mutations are much more frequent than in breast cancers and the therapy may translate to a breast cancer therapy." (PMID 32235312, 2020). "First, DSCAM-AS1 was previously reported to be regulated by ERα 22, 23, 62, 63, and FOXA1 and ERα usually bind together to regulate their target genes in breast cancer, so the dominant expression of DSCAM-AS1 in ER+ breast cancer may be caused by cooperative regulation of FOXA1 and ERα." (PMID 32929382, 2020). "Moreover, neoadjuvant chemotherapy (NAC) could be recommended for breast cancer patients with low FOXA1 expression." (PMID 30819139, 2019). "This is in line with other studies suggesting these SNPs as risk-associated polymorphisms which may lead to a change in the affinity of FOXA1, as a distal enhancer, to TOX3 and thus change in TOX3 expression, which can eventually affect the risk of breast cancer." (PMID 31338012, 2019). "Since the aberrant DNA hypomethylation of promoter regions is one of the mechanisms underlying the aberrant expression of oncogenes in tumors, and the FOXA1 promoter is mostly methylated in ER− tumors, we speculate that FOXA1 functions principally as an oncogene in ER+ breast cancer." (PMID 31562808, 2019).
breast carcinoma (continued). "However, a low FOXA1 alteration frequency was observed in breast cancer." (PMID 31562808, 2019). "Breast cancer patients with tumors expressing FOXA1 may have a better clinical outcome because FOXA1 and GATA3 are expressed in close association with ERα (Estrogen receptor α), by encoding for transcription factors and have a potential involvement in ERα-mediated breast cancer development." (PMID 30819139, 2019). "We further demonstrated that FOXA1 could be related to the ESR1 pathway in breast cancer." (PMID 31562808, 2019). "Thus FOXA1 expression in breast cancer seems to be considerably higher than in FMCs." (PMID 31888566, 2019). "However, the precise role of FOXA1 in breast cancer and the molecular mechanisms underlying its effects have not been elucidated." (PMID 31562808, 2019). "Finally, our results suggest that aberrant DNA hypomethylation of promoter regions contributes to the aberrant expression of FOXA1 in ER+ breast cancer and may be an indicator of favorable prognosis." (PMID 31562808, 2019). "Furthermore, FOXA1 may have a repressive effect on breast cancer growth by regulating the expression of E-cadherin and cell cycle-dependent kinase inhibitor p27." (PMID 31562808, 2019). "A recent research found that breast cancer type 1 susceptibility protein (BRCA1) was related with the suppression of FOXA1 expression in BC cell lines and that BRCA1 mutation was linked to FOXA1 promoter methylation and silencing in BCs." (PMID 31540486, 2019). "Loss of FOXA1 expression in ER+ breast cancers has been associated with resistance to endocrine therapy, thus ER+ FOXA1– FMCs in our cohort may not be hormone-responsive mammary carcinomas." (PMID 31888566, 2019). "Hence, we used proteomic approaches to identify protein targets of FOXA1 for breast cancer cells." (PMID 30572598, 2018). "Interestingly, FoxA1 was found to be a downstream target of another transcription factor GATA3 that has been used as a critical immunohistochemical marker for not only diagnosing breast cancer in surgical pathology practice but also urothelial differentiation." (PMID 30518063, 2018). "Since different molecular mechanisms between AR and FOXA1 signaling pathways have been suggested in ER-negative breast cancers, the clinical implications of AR and FOXA1 status on patient prognosis should be further investigated to improve the survival of patients with heterogeneous breast cancers." (PMID 29137314, 2017). "Because Ell3 is an additional factor to the triple complex of ER(α), GATA3 and FOXA1 and this complex fine-tunes the expression level of IL-20, it will be essential to assess the clinical meaning of the expression of FOXA1 in combination with the expression of Ell3 in ER(α) breast cancer patients." (PMID 28514748, 2017). "For instance, the most strongly associated TF with the AP-1 motif in kidney cancer is RUNX1, while in breast cancer it is FOXA1, suggesting that many of the AP-1 motif-containing sites may require AP-1 dependent de-repression along with positive RUNX1/FOXA activation." (PMID 25994056, 2015). "Collectively, these results suggest that DNA methylation has a part in low FOXA1 expression in basal subtype breast cancers where BRCA1 is either mutated or depleted, highlighting a role of BRCA1 in promoting FOXA1 expression through suppressing FOXA1 methylation in luminal breast cancers." (PMID 25531315, 2015). "Thus, FOXA1 plays a crucial role in determining breast cancer gene expression profiles, and including it in a similar analysis may further improve our understanding of the transcriptional regulation of ERα." (PMID 24792166, 2014). "Although one study reported that FOXA1 expression was correlated with the luminal A subtype and a favorable outcome, others depicted a complicated picture of FOXA1 as a participant in multiple signaling pathways in breast cancer, which are both oncogenic and tumor suppressive." (PMID 23679233, 2013).
breast carcinoma (continued). "Notably, FOXA1, a pioneer factor in development and differentiation, has been suggested to interact with hormonal receptors (ER and androgen receptor) and play a role in breast cancer and prostate cancer, and even in tamoxifen resistance." (PMID 24355041, 2013). "In addition, we provide unanticipated, novel evidence suggesting cooperation between the Wnt1 and ILK pathways, resulting in upregulation of FOXA1/ER-α transcriptional network and the expansion of the luminal progenitor cells, leading to accelerated breast cancer development." (PMID 20565980, 2010). "Therefore, the Wnt1/ILK-mediated upregulation of nuclear β-catenin shown both in vitro and in vivo could potentially be responsible for the observed upregulation of FOXA1 expression in the Wnt1/ILK mammary tumors." (PMID 20565980, 2010). "Based on our results, we can consider that the expression of FOXA1, as an ER-associated gene, may be important to the hormone-responsive phenotype of breast cancer, regardless of the tumour ER status." (PMID 19549328, 2009). "We observed a significant increase in FOXA1 protein expression in MnPP females at PND 30, an ER co-regulator essential for hormone responsiveness in both normal mammary gland development and breast cancer." (PMID 40105700, 2025). "In a luminal breast cancer patient-derived xenograft model, HER2/HER3 signaling increased FOXA1 chromatin binding and reduced sensitivity to ER-targeted treatment." (PMID 41224124, 2025). "FOXA1 is a key transcription factor that mediates the effects of estrogen receptor (ER) and HER2 signaling in breast cancer." (PMID 41224124, 2025). "Regarding RNF220 upregulation, multi-database analysis identified FOXA1 as a negative transcriptional regulator—this epigenetic modulator directly binds androgen receptor promoters, serves as an ER+ breast cancer biomarker, and drives progression in prostate/breast cancers via mutational activation." (PMID 41244923, 2025). "For example, FOXA1, FOXA2, FOXC1, and FOXO3 can all interact with the PI3K/AKT/mTOR pathway and eventually regulate breast cancer cell proliferation." (PMID 40003882, 2025). "One study proposed the possibility of cooperation among several FOX TFs: FOXA1 first turns on chromatin in breast cancer, allowing nearby ER α binding, and then FOXM1 can replace FOXA1 and activate cell cycle genes." (PMID 40003882, 2025). "Altogether, our findings highlight the significance of FOXA1 acetylation, regulated by the HER2/HER3–HDAC2–FOXA1 axis, in controlling FOXA1 chromatin binding and shaping breast cancer progression and therapy response." (PMID 41224124, 2025). "Furthermore, specific DNA methylation biomarkers, including epigenetic modifications in APC, RASSFI, and FOXA1, are emerging as promising candidates for a gene panel that could facilitate the early detection of breast cancer via non-invasive liquid biopsy methodologies." (PMID 40994935, 2025). "FOXA2, which is highly similar to FOXA1 in the DNA-binding domain (DBD), is also considered to play an important role in the regulation of breast cancer." (PMID 40003882, 2025). "To study the FOXA1 gene function, we completed a CRISPR/Cas9 gene KO in HR+ breast cancer cell lines." (PMID 39000600, 2024). "Menin is present at enhancers bound by FOXA1 and GATA3, and menin increases the transcription of multiple genes regulated by these enhancers in ER-positive luminal breast cancer cell lines." (PMID 39336822, 2024). "In this study, we uncovered that well-known TFs, FOXA1 and GRHL2 are key epigenetic regulators distinguishing the diversity of genome-wide chromatin accessibility pattern across breast cancer cell lines." (PMID 38429368, 2024). "Among the diabetes-related genes, FOXA1, MTA3, PAK4, FGFR3, and KIF22 were highly expressed in HR+ breast cancer from 4032 breast cancer patient tissue samples using the Breast Cancer Gene Expression Omnibus." (PMID 39000600, 2024).